PIK3R1 (phosphoinositide-3-kinase regulatory subunit 1)
Diseases named in the same sentence as PIK3R1 in open-access papers (continued):
Sharing a sentence is not in itself a finding about the gene and the disease.
Immunodeficiency (25 papers, 2016 to 2025). Failure of the immune system to protect the body adequately from infection, due to the absence or insufficiency of some component process or substance. "We identified a patient with immunodeficiency and progressive motor neuron disease who carries a novel frameshift c.1710dup mutation in PIK3R1, resulting in PIK3R1 haploinsufficiency." (PMID 40568112, 2025). "This condition occurs because of gain-of-function mutations in the PIK3CD or PIK3R1 genes, which encode the catalytic (p110δ) and regulatory (p85α) subunits of the delta isoform, respectively, resulting in immune dysfunction." (PMID 40978950, 2025). "A human immunodeficiency was reported in patients with mutations in the PIK3R1 gene, suggesting that PI3K activity is critical in the activity of T and B cells." (PMID 35052861, 2022). "Recently described autosomal dominant gain-of-function (GOF) mutations in PIK3CD and PIK3R1 cause combined immunodeficiencies that can also present as CSR/HIGM defects." (PMID 30319630, 2018). "Loss of function mutations in PIK3R1 also occur in immune disorders, with patients identified with autosomal recessive nonsense mutations in PIK3R1 (W298*, R301*) leading to agammaglobulinemia, and severe defects in B-cell development." (PMID 29616047, 2018). "Activating mutations in PIK3R1 have been described in cancers and, more recently, in an immunodeficiency syndrome featuring severely reduced plasma immunoglobulin levels." (PMID 27766312, 2016). "Distinct inter-SH2 domain PIK3R1 mutations, mostly causing skipping of exon 11 and deletion of residues 434–475, hyperactivate PI3Kδ in immune cells, causing highly penetrant monogenic immunodeficiency." (PMID 38077044, 2024). "Mutations in PIK3R1, a regulatory subunit of Class I PI3K, are implicated in immune disorders and neurological conditions." (PMID 40568112, 2025). "This resembles the immunodeficiency reported in Pik3r1 knockout mice and suggests an essential, non-redundant function of p85α in B cell development in humans." (PMID 38077044, 2024). "Activated PI3Kδ syndrome (APDS) is caused by variants in the PIK3CD or PIK3R1 genes, resulting in hyperactivity of the AKT-mTOR-PI3K pathway, as well as progressive immunodeficiency and/or dysregulation." (PMID 39679264, 2024). "One patient with heterozygous PIK3R1 mutation presented the CVID phenotype, and this gene is considered causative of CVID phenotype immunodeficiency." (PMID 35990641, 2022). "Mutations in PIK3CD and PIK3R1, encoding the PI3K p110δ and p85α subunits, respectively, cause increased PI3K activity and result in immunodeficiency with immune dysregulation." (PMID 30891027, 2019). "Diseases involving the PI3K pathway due to PIK3CD and PIK3R1 GOF mutations, have recently been highlighted as forms of combined immunodeficiency compromising both the T- and B-cell compartments." (PMID 30319630, 2018). "PIP2 is in the PI3K signaling pathway, and rare mutations in PIK3R1 (involved in the phosphorylation of PIP2 to PIP3) are associated with an immune deficiency that includes lack of IgA production." (PMID 34976003, 2021). "Notably, from the PPI network, we observed that TNF, STAT3, TLR4, PIK3R1, and HSP90AB1 were significant targets for GAC intervention in CY-induced immunodeficiency." (PMID 37853057, 2023).
lung carcinoma (24 papers, 2013 to 2025). "The promoter hypermethylation of PIK3R1 is significantly associated with gene expression in lung cancer samples (TCGA, LUAD, r = 0.54, P < 2.2 × 10−16)." (PMID 33564067, 2021). "PIK3R1 is frequently mutated in lung cancer and its hypermethylation was significantly associated with gene repression in primary lung cancer samples (TCGA, LUAD, Pearson’s correlation, rho=–0.29, P<0.01)." (PMID 28581523, 2017). "The authors found low PIK3R1 expression in high-risk compared to low-risk lung cancers." (PMID 24229379, 2013). "By targeting IGF1, IGF1R and PIK3R1 this miRNA induces cell cycle arrest and reduces migration of lung cancer cells while acting as a tumour suppressor in a xenograft mouse model." (PMID 34547721, 2021). "It was determined that HSP90AA1 hit downstream genes SRC, PIK3CA, and PIK3R1 to modulate lung cancer progression." (PMID 34833921, 2021). "Although miR-486-5p and PIK3R1 are respectively studied in various cancers, few studies investigate the regulative roles of miR-486-5p and PIK3R1 in lung cancer." (PMID 31402930, 2019). "Although several studies have shown that the expression of PIK3R1 gene is decreased or lost in human cancers, few researches explore the PIK3R1 gene in lung cancer." (PMID 31402930, 2019). "After multiple-testing correction, 112 SNPs in eight genes (ATR, EGFR, MET, PIK3R1, PIK3R3, PTPN2, STAT3, and STAT5A) remained significantly associated with lung cancer risk with FDR <0.20." (PMID 28400551, 2017). "Furthermore, lung cancer tissues exhibited higher expression levels of PIK3R1, AKR1C3, and EGFR when compared to normal lung tissues." (PMID 39204124, 2024). "PIK3R1 also exhibited significant downregulation in colon and lung cancer tissues." (PMID 39204124, 2024). "Therefore, we preferentially selected PIK3R1 as one potential target of miR-486-5p to validate their relations in lung cancer." (PMID 31402930, 2019). "For example, PIK3R1 is a suppressor of the mitogenic AKT pathway, and highly frequent promoter methylation and PIK3R1 has been reported in lung cancer." (PMID 33564067, 2021). "Further investigation showed that miR-345 and miR-498 target mitogen-activated protein kinase 1 (MAPK1) and phosphoinositide-3-kinase regulatory subunit 1 (PIK3R1), respectively, in lung cancer cells." (PMID 33066509, 2020). "Specifically, promoter hypermethylation of PIK3R1, a repressor of the mitogenic AKT pathway, was mainly restricted to lung cancer subtypes." (PMID 28581523, 2017). "PIK3R1, Akt1, and Rheb1 have been identified as important components of PI3K/Akt signaling activation, and they have been suggested as therapeutic targets in lung cancer treatment." (PMID 30987652, 2019). "In lung cancer, miR-486 regulates the insulin growth factor signaling pathway by targeting insulin-like growth factor 1 (IGF1), IGF1 receptor (IGF1R), and phosphoinositide-3-kinase, regulatory subunit 1 (alpha) (PIK3R1)." (PMID 26966540, 2015). "Therefore, the relations between miR-486-5p and PIK3R1 could be well applied in the PI3K-Akt signaling pathway and nonsmall cell lung cancer pathway." (PMID 31402930, 2019).
colorectal cancer (23 papers, 2011 to 2026). A primary or metastatic malignant neoplasm that affects the colon or rectum. "The genes encoding for the beta (PIK3CB) and gamma (PIK3CG) catalytic sub-units and the regulatory sub-unit 1 (PIK3R1) of PI3K were more commonly mutated in CDX2-suppressed colorectal cancers." (PMID 39452477, 2024). "Among the prognostic risk factors, SNRPA1 was reported to be highly expressed in colorectal cancer tissues and promoted cancer progression through the regulation of PIK3R1, VEGFC, MKI67, and CDK1." (PMID 36212157, 2022). "Co-clustering tyrosine phosphosites, PIK3R1 p.Y452/556/580, on the other hand, were observed in endometrial and renal cancer (p.Y580 was also observed in colorectal cancer)." (PMID 33875650, 2021). "Moreover, reduction of PIK3R1 induced apoptosis and cycle arrest in colorectal cancer cells by repressed cyclin D1 expression." (PMID 32817745, 2020). "In addition, a study reported PIK3R1 to counteract TRAIL-induced apoptosis in colorectal cancer cells, confirming a role of PIK3R1 in the regulation of TRAIL sensitivity also in other cancer entities." (PMID 31828111, 2019). "However, PIK3R1 and PIK3CA mutations co-occur in endometrial and colorectal cancers, suggesting that these double events may contribute to pathogenesis in particular tumor types." (PMID 39858051, 2025). "Therefore, we speculated that miR-21 may play a role in the carcinogenesis and development of colorectal cancer by inhibiting PIK3R1 gene." (PMID 32925795, 2020). "Intriguingly, 3 of the genes (IGF1, PIK3R1, and CDH2) of the 10 were targets of miR-221/222-3p, indicating that miR-221-3p and miR-222-3p play undeniable roles in colorectal cancer." (PMID 41602427, 2026). "We reported a novel small RNA sequence, MIRTX, that significantly inhibits KRAS-mutant colorectal cancer cell growth in vitro and in vivo by suppressing NF-kB signaling pathways via direct inhibition of CXCR2 and PIK3R1." (PMID 34834512, 2021). "Additionally, PIK3R1 and PIK3R2 were found to be hypermethylated, specifically in lung and colorectal cancers, respectively." (PMID 33143142, 2020).
diabetes (23 papers, 2003 to 2025). "Among these are genes associated with insulin (MAX, NUCKS1, PIK3R1, PTPN11), diabetes (PIK3R1) and circadian-related processes (HNRNPU, BHLHE41)." (PMID 34745571, 2020). "PIK3R1 (ranked at 1) had been tested for their influence on insulin action, showing significant associations with diabetes." (PMID 21799737, 2011). "Notably, TCF7L2′s ability to modulate PIK3R1 expression suggests its involvement in insulin signaling pathways, potentially mediating diabetes risk through interactions with KLF-14." (PMID 38672763, 2024). "It has been found that PIK3R1 can affect insulin signaling transduction and thus play a direct role in the development of diabetes through insulin resistance signaling." (PMID 35990823, 2022). "The regulatory subunit (p85a), the composition of PI3K, was encoded by PIK3R1, while PI3K signaling was involved in multiple human diseases, including, inflammation, malignant tumor, and diabetes." (PMID 32817745, 2020). "We examined 35 genes predicted to have their major influence on insulin action, and three (9%)—INSR, PIK3R1, and SOS1—showed significant associations with diabetes." (PMID 14551916, 2003). "For FOXO3, MAP3K5, PIK3R1, mitigation of pathological effects of other cardiovascular diseases and/or diabetes represent an additional means whereby individuals with longevity (resilience) genotypes can have a normal lifespan despite possessing one or more of these aging-related conditions." (PMID 37561089, 2023). "For the kinase MAP3K5 it was hypertension, CHD and diabetes, for the kinase receptor PIK3R1 hypertension, CHD and stroke, and for the growth hormone receptor gene (GHR) and vascular endothelial growth factor receptor 1 gene (FLT1), it was nullifying the higher mortality risk posed by hypertension." (PMID 37561089, 2023). "Interestingly, most transcripts namely, Pck2, Prkab2, Pik3r1, Foxo1, Irs1 and Pik3r5 are commonly involved in these pathways and this suggests a significant involvement and contribution of these genes in aberrant skeletal muscle metabolism during diabetes." (PMID 34190986, 2021). "In diabetes mellitus, these signals can be dysregulated via one or several of the proteins driving insulin signaling (AKT1, PIK3R1, INSR, PPARG, and PIK3CG)." (PMID 41011980, 2025). "Finally, we examined the expression of PIK3R1, TPK1, and IPMK in blood samples from 20 people with diabetes before and after intensive insulin therapy." (PMID 40299682, 2025). "Additionally, myricetin and rutin have been shown to modulate various diseases, including diabetes, atherosclerosis, and inflammation-related disorders, through the STAT3, AKT1, and PIK3R1 signaling pathways." (PMID 40356949, 2025). "Notably, the PI3K-Akt signaling pathway, a critical pathway in diabetes, was enriched with additional key targets, including IL6, HSP90AA1, FN1, MAPK1, AKT1, PIK3R1, and MAPK3." (PMID 40170727, 2025). "This suggests that METTL14 might influence insulin signaling transduction to enhance diabetes by regulating the expression of TPK1, IPMK, and PIK3R1." (PMID 40299682, 2025). "While we analyzed the targets and drugs for COVID-19 patients having multiple comorbidities, for diabetes, cancer and COVID-19, PIK3R1 was identified as the only target and there is no approved drug identified through DTP search." (PMID 34067609, 2021). "Upstream regulator analysis suggested COMMD1, HIF1A, EGLN, PIK3R1 and MTORC1 as major upstream regulators for the phase shifts, while HSP90B1, YWHAZ, CNGA3, COL2A1 and TFRC were identified as the major upstream regulators for the amplitude changes observed in the diabetic retina." (PMID 38039846, 2024). "Later detection should be added in patients with only atherosclerosis without diabetes to determine whether the mir-351/ITGB3/PIK3R1/Akt pathway is also affected." (PMID 36180828, 2022).
diabetes (continued). "Further correlation analysis indicated the key molecules involved in PI3K-AKT signaling pathway, such as AKT1, AKT2, PIK3R1, and PIK3R2, showed significant positive correlations with AFAP1L2, and in which AKT1 also showed elevated expression in patients without diabetes history." (PMID 36434634, 2022).
ovarian carcinoma (21 papers, 2012 to 2025). A malignant neoplasm originating from the surface ovarian epithelium. "This is in agreement with a study of a pan-cancer cohort across 20 different cancer types, including ovarian cancer, in which only 2 patients out of the 1200 analyzed harbored both a PIK3R1 and a PIK3CA mutation." (PMID 39858051, 2025). "In summary, we showed that the PIK3R1 gene is frequently altered in ovarian cancers due to mutations, DNA copy number alterations, and decreased PIK3R1 mRNA expression." (PMID 39858051, 2025). "In another study, PIK3R1 copy number loss or reduced PIK3R1 expression rendered ovarian cancer cells vulnerable to the inhibition of AKT or JAK2/STAT3 inhibitors." (PMID 39858051, 2025). "The present study aimed to evaluate PIK3R1 status in ovarian carcinomas by analyzing mutations, copy number alterations, and mRNA expression, in the context of the clinicopathological features of these tumors." (PMID 39858051, 2025). "PIK3R1 mutations are infrequent in ovarian cancers, except for the endometrioid and clear-cell types, in which they have been detected with a frequency ranging from 7% to 50%." (PMID 39858051, 2025). "In ovarian cancers, PIK3CA mutations seem to be the primary somatic mutations, comprising approximately 12% missense mutations in epithelial ovarian cancers while PIK3R1 mutations are found in 3.8% of ovarian cancers." (PMID 38396649, 2024). "Loss of PIK3R1 in ovarian cancer is a common event, which provides opportunities for therapeutic intervention." (PMID 30755611, 2019). "Collectively, these data indicate that ovarian cancer cells with PIK3R1 loss demonstrate multiple tumorigenic properties, providing an explanation of the frequent PIK3R1 copy number loss in the disease." (PMID 30755611, 2019). "Instead, the oncogenic phenotypes promoted by PIK3R1 loss in ovarian cancer are likely mediated by matrix metalloproteinases and cell cycle proteins." (PMID 30755611, 2019). "Given the high occurrence of copy number loss and the context-dependent molecular manifestations of the aberration in different cancer lineages, we sought to determine the functional role and therapeutic implication of PIK3R1 loss in ovarian cancer." (PMID 30755611, 2019). "We did not detect changes in expression or degradation-mediating phosphorylation (T41/S45) of β-catenin in any PIK3R1-depleted ovarian cancer cell lines, suggesting a tissue specific function of PIK3R1 loss." (PMID 30755611, 2019). "Further, the activated signaling creates a targetable therapeutic vulnerability in PIK3R1 loss-bearing ovarian cancer cells." (PMID 30755611, 2019). "Together, these results suggest that the dual inhibition of JAK2/STAT3 and AKT demonstrates striking antitumor effect in ovarian cancer cells with PIK3R1 loss." (PMID 30755611, 2019). "We also provide a rationale for mechanism-based therapy involving dual inhibition of STAT3 and AKT signaling in ovarian cancer with PIK3R1 loss or low p85α level." (PMID 30755611, 2019). "In summary, our comprehensive functional characterization of PIK3R1 loss in ovarian cancer provides an explanation for the frequent PIK3R1 deletion that occurs in the disease." (PMID 30755611, 2019). "Five PIK3R1 mutations were identified in 141 (3.5%) ovarian carcinomas." (PMID 39858051, 2025). "Together, these data support the function of PIK3R1 as a tumor suppressor, the loss of which may enhance tumorigenesis in ovarian cancer and other cancer types." (PMID 39858051, 2025). "However, a small fraction of PIK3R1 allele amplification (3.3%) was also observed in TCGA ovarian cancer patients." (PMID 39858051, 2025). "PIK3R1 is a p85 regulatory protein encoded by the Phosphatidylinositol-kinase regulatory subunit alpha gene that regulates the p110 catalytic subunit, where most frequent mutation occurs in ovarian cancer and endometrial carcinomas, within the iSH2 domain." (PMID 36608061, 2023).